INS (insulin)
Diseases named in the same sentence as INS in open-access papers (continued):
Sharing a sentence is not in itself a finding about the gene and the disease.
diabetes (continued). "The focus of many recent studies on obesity and diabetes is to determine the efficacy of natural compounds with the dual function of increasing serum insulin levels and decreasing glucose levels." (PMID 26989693, 2016). "In order to investigate insulin-mimetics effects of decavanadate we develop a model insulin-requiring by alloxan injection in which observed insulin depletion with hyperglycemia that produces an increase of glycohemoglobin occurs in type 1 diabetes mellitus." (PMID 27119007, 2016). "Patients with diabetes who were taking insulin used more transportation (and therefore required more time) than those on no or oral medication." (PMID 27142529, 2016). "The predictive factors included an older age, a longer diabetes duration, male sex and use of insulin, sulfonylurea, calcium channel blockers and anti-platelet drugs." (PMID 27409676, 2016). "As for the treatment of diabetes 23.2% of patients were treated with insulin, 25.3% with oral diabetes medications, 3% with both insulin and oral diabetes medications, and 8.1% with lifestyle modifications." (PMID 27814399, 2016). "DMT2 is the major common form of diabetes, and is characterized by a combination of factors including resistance to insulin action and inadequate compensatory insulin secretory response." (PMID 28042834, 2016). "Using a cross-sectional, population-based study, we assessed BMI, plasma insulin and the evidence of diabetes in homebound elders." (PMID 27642517, 2016). "Insulin therapy is generally preferred because of its superior results in controlling diabetes, in addition to being more predictable and rapidly titrated." (PMID 28702248, 2016). "The strongest explanatory variables for PAI-1 in the multiple regression analysis after adjusting for age and BMI among metabolic parameters were insulin and triglycerides levels as well as duration of diabetes." (PMID 26940634, 2016). "Insulin use, however, was recorded on the last follow-up medical questionnaire among men who were diagnosed with diabetes on the basis of fasting plasma, and only 2.7% (13 of 477) reported insulin use." (PMID 27340824, 2016). "She received insulin therapy for her diabetes mellitus, and her subsequent clinical course has been uneventful." (PMID 27520566, 2016). "STZ can result in the damage of the insulin-producing beta cells in the mammalian pancreas, and it has also been used for inducing diabetes in experimental animals for a long time." (PMID 27257845, 2016). "Diabetes and insulin resistance are associated with defects in glucose uptake, while GTTs and ITTs revealed a positive regulatory role of miR-155 in glucose tolerance and insulin sensitivity, further supporting the hypothesis that miR-155 might drive increased glucose uptake." (PMID 27711113, 2016). "Both glibenclamide and insulin treatment also reversed the ultrastructural and histochemical changes induced by diabetes but the time course was very different." (PMID 27882918, 2016). "Here, we show that diabetes prevention in STZ-treated Gcgr-/- animals requires remnant insulin action originating from spared residual β-cells: these mice indeed became hyperglycemic after insulin receptor blockade." (PMID 27092792, 2016). "Higher number of insulin injections and lower number of OADs were used, whereas a lower level of knowledge and a higher level of diabetes-related distress were reported in LA." (PMID 27453733, 2016). "Oral glutamate supplements have been reported to impair insulin sensitivity and to induce the development of diabetes in animal studies." (PMID 26788116, 2016). "Type 1 diabetes mellitus (T1D) is characterized by autoimmune responses resulting in destruction of insulin-producing pancreatic beta cells." (PMID 26781648, 2016). "This is the first community-based study we know of to examine premorbid intelligence with regard to obesity, elevated insulin and diabetes in elderly." (PMID 27642517, 2016).
diabetes (continued). "We have shown that the IL-1βR antagonist SER140 at 10 mg/kg subcutaneously is able to prevent the destruction or damaging of the insulin producing β-cells and hence reduce the incidence of diabetes in female NOD mice." (PMID 26953152, 2016). "Diabetes mellitus is a group of metabolic disorders, characterized by hyperglycemia resulting from the defects in insulin secretion, insulin action, or both." (PMID 26925100, 2016). "The defective insulin secretion, exhibited by both diabetes types albeit to varying degrees, affects glucose homeostasis." (PMID 27602200, 2016). "Surprisingly Japanese women and men with diabetes not only had much lower insulin levels than Framingham counterparts with diabetes, but also had significantly lower levels than their NGT counterparts in Framingham." (PMID 27830830, 2016). "To date, main therapeutic approach in treating diabetes is to improve insulin resistance, promote insulin secretion, or preserve the remaining beta cell function by using insulin or drugs." (PMID 27242389, 2016). "On bivariate analysis, ELC was associated with diabetes and several markers of insulin resistance such as lower HDL cholesterol and higher glucose, insulin, HOMA-IR and triglycerides levels." (PMID 26790748, 2016). "From the Diabetes Prevention Program, we know that low insulin secretion and low insulin sensitivity at baseline generally predict higher diabetes risk regardless of the treatment regime." (PMID 26643313, 2016). "These medications were predominantly antiallergic drugs (salbutamol and/or salmeterol /fluticasone) and drugs for attention-deficit hyperactivity (methylphenidate) or diabetes (insulin)." (PMID 27550850, 2016). "B6.g7 mice express the same MHC Class II allele as NOD mice, have predominantly naïve insulin-specific CD4+ T cells in the periphery, and remain diabetes-free even after PD-1 pathway blockade." (PMID 27656680, 2016). "Diabetes mellitus is one of the most prevalent chronic diseases characterized by elevated blood glucose levels due to defects in insulin secretion or its action." (PMID 26984821, 2016). "Our results establish TSC22D4 as a checkpoint in systemic glucose metabolism in both mice and humans, and propose TSC22D4 inhibition as an insulin sensitizing option in diabetes therapy." (PMID 27827363, 2016). "Together with our previous study, which showed only a 46% and 30% suppression of diabetes in mice fed CTB-insulin at 35 weeks of age, as compared with 62% suppression of diabetes in mice fed CTB-Ins-GAD (62% vs 46%, p<0.05; 62% vs 30%, p<0.05)." (PMID 26783749, 2016). "First, the study was designed as a retrospective study, and thus the period from the diagnosis of diabetes to the examination of the GADAb level and the timing of initiation of insulin treatment were left to the treating physicians." (PMID 27177031, 2016). "Before the discovery of insulin in 1921, diabetes controlling was referred to the prevention of early death from the disease." (PMID 27047810, 2016). "Diabetes mellitus (DM) is an endocrine disease of the dog characterised by hyperglycaemia, glycosuria and weight loss, which is caused by an absolute or relative deficiency in the pancreatic beta-cell hormone insulin." (PMID 27203422, 2016). "Mean change of VAS score from V1 to V4 was also analyzed for the subgroups: Type of diabetes, Insulin regimen application and Age." (PMID 27625706, 2016). "In fact, insulin rises dramatically in concert with insulin resistance in the early diabetes of NRs fed high-glycaemic load diets, then falls as diabetes progresses." (PMID 27795741, 2016). "In diabetes increased ROS levels lead to repression of insulin synthesis through enhancing apoptosis of pancreatic beta-cells." (PMID 27980584, 2016). "Diabetes mellitus is a disease characterised by chronic hyperglycaemia due to defects in insulin secretion, insulin action or both." (PMID 27029351, 2016).
diabetes (continued). "Initial studies to determine if hyperglycemia affected B. burgdorferi dissemination and clearance were performed in the most widely reported mouse model of insulin-insufficient diabetes, low dose streptozotocin (STZ)-treated C57BL/6 mice." (PMID 27340827, 2016). "Mitochondria play an imperative role in glucose metabolism, insulin secretion and biogenesis, hence its dysfunction is reportedly found to play a crucial role in diabetes development." (PMID 27350825, 2016). "The results revealed that the aqueous stem bark extract of G. arborea (1.00 g/kg) showed beneficial effects against diabetes mellitus through upregulating the β-cell regeneration and biosynthesis of insulin in diabetic rats." (PMID 26881248, 2016). "In spite of current guidelines and diabetes technology such as insulin pump therapy and continuous glucose monitoring, avoiding exercise related dysglycaemia remains a challenge for many individuals with type 1 diabetes." (PMID 27287376, 2016). "Overall, our analysis demonstrates that bariatric surgery for severely obese type 1 diabetes mellitus (T1DM) patients offers a significant reduction in biochemical markers of diabetes status and insulin requirements." (PMID 26694210, 2016). "The neuroendocrine effects of leptin on metabolism hold promise to be translated into a complementary therapy to traditional insulin therapy for diabetes and obesity." (PMID 27055280, 2016). "There are, however, controversial reports in the literature on the effect of insulin alone or in combination with OHA on cognitive function in diabetes." (PMID 27195294, 2016). "Defective brain glucose metabolism is another common feature of diabetes and AD because insulin signaling is altered by Aβ." (PMID 27242668, 2016). "For diabetes, the most relevant components of metabolic capacity are the function of the pancreas (responsible for producing insulin) and muscle mass (influencing glucose clearance rate), each of which is strongly contingent on fetal and infant growth." (PMID 27458578, 2016). "Other clinically evaluated control approaches include the fuzzy logic approach, which modulates insulin delivery on the basis of approximate rules to express empirical knowledge acquired by diabetes practitioners." (PMID 27364997, 2016). "Cytotoxic T lymphocytes execute the killing of insulin-producing beta cells during onset of type 1 diabetes mellitus (T1D)." (PMID 27574523, 2016). "Increasing duration of diabetes is associated with increased CVD risk, as well as a likely need for insulin therapy." (PMID 27188479, 2016). "Optimal cut-off values of GADAb level, age at diabetes onset, duration before diagnosis of GADAb-positive diabetes, and FCPR for a progression to insulin-requiring diabetes by ROC curve analysis." (PMID 27177031, 2016). "To dissect such actions of exendin-4 in experimental diabetes, we performed comprehensive metabolic assessment of our animals and also included an insulin comparator group." (PMID 26597728, 2016). "These implanted devices resulted in positive reversal of diabetes in fourteen of the patients for two years post-implantation, showing a 60–65 % decrease in exogenous insulin needed and a complete disappearance of hypo- or hyperglycemia related comas." (PMID 28191438, 2016). "Hepatic insulin resistance results in impaired insulin-induced suppression of gluconeogenesis in obese subjects, and gluconeogenesis closely correlates with the severity of diabetes and the degree of obesity." (PMID 27213439, 2016). "Type 2 diabetes mellitus describes a condition of fasting hyperglycemia that occurs despite the availability of insulin." (PMID 27294153, 2016). "It is known that the acute exercise makes skeletal muscle more sensitive to insulin while lifestyle modification though regular (chronic) exercise reduces the incidence of subsequent diabetes by 60%." (PMID 28248217, 2016).
diabetes (continued). "The clinical criteria that suggest the need for the initiation of insulin therapy in diabetes are dehydration, ketosis, and acidosis." (PMID 27974926, 2016). "These patients were older, had a longer diabetes duration, were more likely to be on insulin treatment, and had a higher prevalence of microalbuminuria." (PMID 27200379, 2016). "Consistent with this, animal models of diabetes also show increased insulin secretion in early disease." (PMID 27048248, 2016). "A diabetes self-management app similarly incorporated an algorithm to calculate the required insulin bolus amount depending on blood glucose levels before meals, carbohydrate counts, and planned physical activity that were manually entered into the program." (PMID 26831935, 2016). "In a candidate gene study within the Amish Family Diabetes Study (AFDS), the authors demonstrated that haplotype of a subtype of taste receptor (TAS2R9) is associated with altered glucose and insulin homeostasis." (PMID 27382574, 2016). "For TG levels, diabetes on insulin therapy was a confounding factor, potentially influencing the effect of the dietary intervention on serum TG levels." (PMID 28076479, 2016). "PPARγ is a primary target for thiazolidinedione-structured insulin sensitizers like pioglitazone and rosiglitazone employed for the treatment of type 2 diabetes mellitus." (PMID 27955667, 2016). "Forty-two percent were using insulin for their diabetes, and participants on average had had a diabetes diagnosis for 12 years." (PMID 26741995, 2016). "Append to IR, impaired insulin secretion has a critical role in the development of diabetes, in hoc, it is noticeable that BCAAs are modulators of insulin secretion." (PMID 28053823, 2016). "Long-term studies in animal models of diabetes are required to evaluate the capacity of these insulin-producing cells to maintain glucose homeostasis, for use in the treatment of type 1 diabetes mellitus." (PMID 27567623, 2016). "The RCOD missed a total of 562 patients (mean age = 10.3 ± 4.9 years, 52.8% males) of which 35.2% (198/562) were hospitalized, 43.8% (246/562) were entitled to fee exemption for diabetes, and 66.4% (373/562) had drugs prescriptions for insulin or analogues." (PMID 27092312, 2016). "The evaluated predictors included age, sex, diabetes duration, diabetes type, body mass index, insulin use, hypertension, smoking, living region and screen-detected diabetes." (PMID 27906989, 2016). "Considering that our subjects had new onset pre-diabetes/diabetes, the total insulin secretion increased under the conditions of hyperglycemia." (PMID 27267043, 2016). "In the setting of diabetes, it has been recently shown that liver-specific miR-26a plays a crucial role in the regulation of insulin sensitivity and glucose metabolism in obese mice and human." (PMID 27005938, 2016). "STZ is synthesized by Streptomycetes achromogenes and is used to induce both insulin-dependent and non-insulin-dependent diabetes mellitus based on the STZ dose." (PMID 27175212, 2016). "The increases in blood glucose, free fatty-acid and insulin levels in tolbutamide-treated gerbils were more dramatic than rat model of diabetes." (PMID 27427908, 2016). "Diabetes is a metabolic disease characterized by hyperglycemia, reduced glucose tolerance, and insulin-releasing abnormalities." (PMID 27088095, 2016). "Both diabetes-exposed (p = 0.002) and HF diet-exposed (p = 0.009) newborn offspring had higher serum insulin levels leading to a 10-fold higher average circulating insulin level in combination-exposed pups compared to controls." (PMID 27518105, 2016). "Since then, it was found that there was down-regulation of rat glomerular insulin signaling in diabetes attributed to excessive PKCβ activation." (PMID 27434075, 2016).
diabetes (continued). "Understanding the complex mechanisms that regulate insulin response and the onset of peripheral insulin resistance represents a primary goal in the treatment of diabetes and obesity complications, particularly by targeting skeletal muscle." (PMID 26697506, 2016). "The purpose of the study was to determine the effectiveness of insulin loaded mucoadhesive devices in the treatment of diabetes through assessment of blood glucose lowering effect in both normal and diabetic rats." (PMID 29313019, 2016). "Dysfunction of beta cell lead to altered insulin production and secretion resulting in hyperglycemia and glucose intolerance manifesting to diabetes mellitus." (PMID 27547752, 2016). "Smart therapies can improve diabetes control and reduce the potential for ultralow BGLs, which is a potentially deadly consequence of excessive insulin dosing." (PMID 27792179, 2016). "The correlation of systolic strain and diastolic strain rates with hepatic and epicardial fat and insulin resistance suggests a link between these in patients with diabetes." (PMID 27364051, 2016). "This review summarizes the interactions of AD and diabetes from the cell biology to the patient level and the clinical results of intranasal insulin treatment of cognitive decline in AD." (PMID 27240327, 2016). "Considering that metformin is a first line treatment for T2D and that sulphonylurea and insulin are also very common therapeutic tools in diabetes, more CVOTs on these drugs are essential." (PMID 27716274, 2016). "α-lipoic acid has shown beneficial effects both in the prevention and in the treatment of diabetes because of its insulin-mimetic and anti-inflammatory action; it is also involved in mitochondrial bioenergetic reactions." (PMID 27801825, 2016). "It is reported that TNF-α is a possible mediator of insulin resistance and diabetes since it inhibits insulin signaling and impairs its secretion." (PMID 27478850, 2016). "A large number of studies now show that peer support helped patients with diabetes increase physical activity, perform self-monitoring of blood glucose, adhere to balanced diet, and initiate insulin therapy." (PMID 27796780, 2016). "The efficacy and safety of insulin degludec/insulin aspart (IDegAsp) once daily (OD) compared with insulin glargine U100 (IGlar) OD over 52 weeks in insulin-naïve adults with type 2 diabetes mellitus (T2DM) was investigated." (PMID 27760129, 2016). "Previous studies suggest that before insulin secretion fails and diabetes manifests, β-cells in elderly subjects try to compensate for insulin resistance with increased insulin secretion to prevent disease." (PMID 27029739, 2016). "The dependency of chicory action on the presence of insulin indicates its usefulness in the early stages of diabetes and for the purpose of preventing and delaying diabetes onset." (PMID 26877773, 2016). "The second case-patient was a 71-year-old man with diabetes who had been undergoing insulin therapy for 20 years." (PMID 26982379, 2016). "Levels of metabolic analytes were similar in patients with diabetes and hyperlipidemia, with some exceptions; fasting glucose and fasting insulin decreased through week 12, and hemoglobin A1C decreased slightly through week 24 in patients with diabetes." (PMID 27704313, 2016). "Neonatal diabetes mellitus (NDM) is a severe and monogenic form of diabetes mellitus (DM) which is characterized by the onset of insulin-requiring hyperglycaemia within the first months of life." (PMID 27832816, 2016). "A challenge faced in reproducing this phenomenon in diabetic rats appears to be the need for a higher dosage of insulin to overcome insulin resistance and the altered counterregulatory response due to the diabetes itself." (PMID 27843452, 2016). "Mitogen activated protein kinase 8 interacting protein 1 also called islet brain 1 (IB1) is a candidate gene for diabetes that is required for beta cell survival and glucose-induced insulin secretion (GSIS)." (PMID 26665154, 2016).